LATS1 (large tumor suppressor kinase 1)
Diseases named in the same sentence as LATS1 in open-access papers (continued):
Sharing a sentence is not in itself a finding about the gene and the disease.
breast cancer (continued). "Overall, this implies that LATS1 is important for maintaining luminal breast cancer-associated expression patterns; without it, tumors may become more basal-like, even within an otherwise lumB-predisposed in vivo setting." (PMID 30456386, 2018). "Hence, these two closely related paralogs play distinct roles in protection against breast cancer; tumors with reduced expression of either LATS1 or LATS2 may rewire signaling networks differently and thus respond differently to anticancer treatments." (PMID 30456386, 2018). "Furthermore, in agreement with the known ability of hyperactive YAP/TAZ to augment cell proliferation, LATS1 silencing in human luminal breast cancer-derived cells yielded a transcriptional signature strongly enriched for cell cycle and mitosis-related pathways." (PMID 30456386, 2018). "In breast cancer, the long non-coding RNA SNHG9 interacts with PA and LATS1, facilitating phase separation of LATS1 and modulating the YAP signaling pathway, thereby influencing malignant progression." (PMID 41502512, 2025). "NUAK2 acts as a potent YAP/TAZ activator, inhibiting LATS1/2 kinase activity, leading to nuclear accumulation of YAP and ultimately tumorigenesis in liver and breast cancers." (PMID 40770117, 2025). "In mammary epithelial cells and breast cancer cells, PI3K and phosphoinositide‐dependent kinase (PDK1) act as upstream negative regulators of LATS1/2, thereby promoting YAP nuclear localization, and PI3K inhibitors block YAP nuclear localization." (PMID 40661662, 2025). "LATS1 and LATS2 (LATS1/2) are Hippo pathway kinases that inhibit YAP/TAZ nuclear translocation and transcriptional activity and function as potential tumor suppressors in breast cancer." (PMID 40622584, 2025). "We previously demonstrated that deletion of the Lats1 and Lats2 genes in luminal mammary cells induces luminal-basal plasticity and YAP/TAZ-mediated development of basal-like mammary carcinomas." (PMID 39953252, 2025). "Here, we demonstrated that LATS1 mRNA m6A modification mediated by METTL3 and recognized by YTHDF2, plays a positive role in promoting both tumorigenesis and glycolysis in breast cancer." (PMID 36609396, 2023). "In breast cancer, the MGO-altered heat shock protein 90 decreased the LATS1 expression, a kinase of the Hippo tumor suppressor pathway, enhancing growth and metastatic potential in vivo." (PMID 37174618, 2023). "We demonstrated that Mettl3-mediated m6A methylation of LATS1 mRNA is recognized by YTHDF2, which reduces LATS1 expression and inactivates the Hippo pathway in breast cancer." (PMID 36609396, 2023). "To determine the mechanism of m6A modification of LATS1 in breast cancer, we used SRAMP to predict the m6A sites in LATS1 mRNA." (PMID 36609396, 2023). "Altogether, retention of proper LATS1 and NCOR1 activity appears to be beneficial for the survival of luminal breast cancer patients." (PMID 36443319, 2022). "In ER + breast cancer cells, CRABP2 suppresses tumor metastasis by inhibiting ubiquitination of Lats1; while CRABP2 enhances ubiquitination of Lats1 and promotes tumor metastasis." (PMID 36568517, 2022). "Consistent with our findings, a recent study showed that LATS1/2 maintained ESR1 expression and ER+ breast cancer growth by inhibiting YAP/TAZ40." (PMID 35654829, 2022). "Together, these results strongly suggest that LATS1 augments NCOR1-driven gene repression to promote luminal fate in human and mouse breast cancer cells." (PMID 36443319, 2022).
breast cancer (continued). "The staining patterns of LATS1 and NCOR1 proteins were remarkably similar in PyMT mouse and MCF7 human mammary carcinoma cells." (PMID 36443319, 2022). "Similar elevated nuclear YAP/TAZ was observed in Lats1/2f/f; lsl-EYFP; Sox9CreERT2 mammary carcinomas." (PMID 36443313, 2022). "We therefore conclude that RASSF1A executes its tumor-suppressor functions in ERα-driven breast cancer cells through LATS1 and LATS2, and that mutual interaction between RASSF1A and LATS1 and LATS2 are important for the suppression of ERα+ breast cancer." (PMID 34831091, 2021). "Nevertheless, Ho and colleagues discovered that AIP4 promotes degradation of LATS1 to enhance nuclear translocation of YAP and thus increases breast cancer cell proliferation while reducing apoptosis." (PMID 35177982, 2021). "The downregulation of LATS1 and LATS2 has been observed in astrocytoma, breast cancer, colon cancer, gliomas and non-small cell lung cancer, and is directly associated with a poor prognosis." (PMID 33411690, 2020). "In this study, we evaluated the effect of quinacrine on expression of LATS1, LATS2, and YAP genes of the Hippo signaling pathway and YAP level in human breast cancer stem cells (MDA-MB 231 cell line)." (PMID 33247672, 2020). "In epithelial breast cancer cells, Scribble facilitates interactions between the core Hippo kinases (MST1/2 and LATS1/2) and TAZ, which acts as a scaffold protein, thereby destabilizing and preventing activation of TAZ." (PMID 30800215, 2019). "Knocking down LATS1 partially reduced the effects of elevated FRY in inhibiting the growth and proliferation of breast cancer cells." (PMID 31824855, 2019). "In ER− mammary cancer cells, the interaction of exogenous CRABP2 and Lats1 through an E3 ubiquitin ligase promotes the ubiquitination of Lats1 to promote the invasion and metastasis of ER− mammary cancer." (PMID 31419991, 2019). "Here we investigated the mRNA expression of Lats1 when knocking down CRABP2 in ER+ and ER− mammary cancer cells." (PMID 31419991, 2019). "In ER+ mammary cancer cells, the interaction of CRABP2 and Lats1 suppresses the ubiquitination of Lats1 to activate Hippo pathway to inhibit the invasion and metastasis of ER+ mammary cancer." (PMID 31419991, 2019). "By analyzing the mRNA microarrays from TCGA, we determined that LATS1/2 level was positively correlated with STARD13, CDH5, HOXD1, and HOXD10 levels in breast cancer tissues, respectively." (PMID 29848346, 2018). "Altogether, our findings imply that deregulation of LATS1 and LATS2 can exert both common and distinct effects on breast cancer progression, by interaction with a variety of regulatory pathways." (PMID 30456386, 2018). "Notably, LATS1/2 could suppress breast cancer EMT and metastasis via inactivating YAP/TAZ activity." (PMID 29848346, 2018). "We provide evidence that both LATS1 and LATS2 are bona fide tumor suppressors in an in vivo breast cancer setting." (PMID 30456386, 2018). "Consistently, ectopic expression of STARD13-correlated ceRNAs-3′UTRs in breast cancer cells elevated LATS1/2 levels, while the knockdown of STARD13-correlated ceRNAs decreased LATS1/2 levels." (PMID 29848346, 2018). "In this context, while over-expression of WWP1 enhances cell proliferation in LATS1-positive MCF10A mammary epithelial cells, knockdown of WWP1 in MCF7 breast cancer cells reduces their proliferation." (PMID 30619734, 2018). "Previous studies have shown that LATS1 expression is downregulated in malignant tumors, including CSCC, breast cancer and HCC." (PMID 26921249, 2016). "Downregulation of LATS1 and LATS2 mRNA expression by promoter hypermethylation has been reported in breast cancer." (PMID 26942001, 2016). "Since down-regulation of LATS1 and over-expression of WWP1 was shown to be involved in the development of breast cancer, we further explored the physical and functional interaction of WWP1 and LATS1." (PMID 23573293, 2013).
breast cancer (continued). "In fact, the LATS1/2 kinases upstream of YAP1 have been shown to be down-regulated in several cancer types including soft tissue sarcoma, astrocytoma, and breast cancer." (PMID 22396793, 2012). "In mammary tumors, in MLPD-like leukemias and in uterine tumors, Lats1 mRNA expression was consistently elevated in tumors as compared to control normal tissues." (PMID 19656388, 2009). "Depletion of ST6GAL1 results in increased phosphorylation of large tumor suppressor kinase 1 and YAP, which induces YAP's nuclear localization, transcriptional activity, and multiple biological functions in breast cancer cells, including cell adhesion, spreading, growth, migration, and metastasis." (PMID 40409546, 2025). "Moreover, seven in absentia homolog 2 inhibits LATS2 to stimulate YAP, and LATS1/2 maintains estrogen receptor alpha (Erα) expression by inhibiting YAP/TAZ, thereby promoting the growth of ERα+ breast cancer cells." (PMID 40066231, 2025). "We show that conditional luminal-specific inactivation of LATS1/2 in the adult mouse mammary epithelium leads to YAP/TAZ-driven luminal-basal plasticity and rapid initiation of basal-like carcinomas that strongly resemble human basal-like breast cancers." (PMID 36443313, 2022). "Importantly, also in human luminal breast cancer MCF7 cells, depletion of either NCOR1 or LATS1 increased the levels of H3K27ac and upregulated NCOR1-repressed genes." (PMID 36443319, 2022). "The degradation of LATS1 is important for WWP1-induced increased cell proliferation in breast cancer cells, opening a novel strategy to develop drugs targeting WWP1 for suppressing breast cancer cell growth." (PMID 35205738, 2022). "The loss of RASSF1A or aberrations in the function of the Hippo-kinases LATS1 and 2 might shift the balance towards increased activation of YAP1, FOXM1 and ERα, fostering luminal breast cancer initiation and progression." (PMID 34831091, 2021). "Furthermore, our results support the notion that the Hippo pathway is important for the suppression of luminal breast cancers, and that the tumor-suppressor function of RASSF1A depends on LATS1 and LATS2." (PMID 34831091, 2021). "Our analysis of drug‐resistant breast cancer cells indicated that MET increased SCRIB expression, which then recruited MST1/2 and LATS1 to the plasma membrane, leading to YAP phosphorylation and its retention within the cytoplasm, and finally to inhibition of cell proliferation and invasion." (PMID 32281270, 2020). "However, the protein expression of p-Lats1T1079, Lats1, p-YAPS127 in the Hippo pathway were reduced, maintaining the expression levels of YAP and Mst2 when knocking down CRABP2 in ER+ breast cancer cells." (PMID 31419991, 2019). "However, after knocking ER down in ER+ breast cancer, the reason for that CRABP2 overexpression still can stabilize Lats1 needs to be further explored." (PMID 31419991, 2019). "Our results demonstrated that CRABP2 affected the protein level and not the mRNA level of Lats1 in mammary cancer cells." (PMID 31419991, 2019). "However, in ER− mammary cancer cells, the interaction of CRABP2 and Lats1 promote the ubiquitination of Lats1 to inactivate Hippo pathway to promote the invasion and metastasis of ER− mammary cancer." (PMID 31419991, 2019). "However, in ER− mammary cancer cells, the interaction of CRABP2 and Lats1 promotes the ubiquitination of Lats1 to inactivate Hippo pathway to promote the invasion and metastasis of ER− mammary cancer." (PMID 31419991, 2019). "Interestingly, we have also found that m6A levels in the large internal exons of LATS1 and BRCA1 are significantly lower in pPA-activated breast cancer cells relative to untransformed mammary cells." (PMID 29362392, 2018).
breast cancer (continued). "Accordingly, when we overexpressed LATS1, we were able to revert MG effects on YAP accumulation as assessed by immunofluorescence using two anti-YAP antibodies in MDA-MB-231 cells, and in the other breast cancer cell lines analyzed." (PMID 27759563, 2016). "Whereas LATS1 protein was constitutively expressed at low levels, LATS2 protein was highly expressed under non-hypoxic conditions and expression was dramatically decreased under hypoxic conditions in the four breast cancer cell lines that were analyzed." (PMID 25587023, 2014). "In breast cancer, it has been shown that WWP1 is an oncogene and LATS1 is a tumor suppressor gene." (PMID 23573293, 2013). "Lastly, to define whether inactivation of LATS1/2 and activity of YAP/TAZ/TEADs correlate with similar stromal phenotypes in human breast cancer, we used TIMER, which is a computational platform that estimates stromal cell infiltration based on RNA-seq data from The Cancer Genome Atlas (TCGA)." (PMID 39953252, 2025). "When DNAJB4 was knocked down and then overexpressed in MDA-MB-231 and BT-549 breast cancer cells, Western blot analysis showed that the phosphorylation levels of MST1, LATS1, and YAP were restored, while the total protein expression of MST1, LATS1, and YAP1 remained unchanged." (PMID 37012515, 2023). "Here we show that RASSF1A depends on LATS1 and LATS2 for the execution of its tumor-suppressor functions in ERα-driven breast cancer cells and suggests that the mutual interaction between RASSF1A and the Hippo-kinases LATS1 and LATS2 is important for the suppression of ERα+ breast cancers." (PMID 34831091, 2021). "Consistent with this notion, the loss of heterozygosity of LATS1 and frequent copy number loss of LATS2 has been reported in breast cancer, suggesting that partial but not complete inactivation of LATS kinases is important for breast cancer development." (PMID 34831091, 2021). "Although partially contradictory, these studies nevertheless suggest that partial but not complete inactivation of LATS kinases is important for breast cancer development, and that LATS1 and 2 do not only act as tumor suppressors, consistent with other observations." (PMID 34831091, 2021). "To investigate whether LATS1 and/or LATS2 are indeed responsible for RASSF1A-mediated suppression of YAP1, ERα and FOXM1 expression in ERα+ breast cancer cells, we employed stable knockdown of either LATS1, LATS2 or LATS1+LATS2 in RASSF1A-conditional MCF7 cells." (PMID 34831091, 2021). "a-b Knockdown of Lats1 in ER- breast cancer cells could not modify the mRNA and protein expression of CRABP2." (PMID 31419991, 2019). "Knockdown of Lats1 in ER+ breast cancer cells could not modify the mRNA and protein expression of CRABP2." (PMID 31419991, 2019). "Finally, we analyze public expression data and find that other TSGs, including LATS1 and BRCA1, also undergo intronic pPA following large internal exons, and that m6A levels in these exons are reduced in pPA-activated breast cancer cells relative to untransformed mammary cells." (PMID 29362392, 2018). "During the treatments with veliparib and ponatinib, SNVs occurred on or near LATS1 (a core component of Hippo-YAP pathway), MGMT (related to DNA damage), IL17RB (related to NF-κB signaling) and APCDD1L (related to wnt signaling), all of which are known to be related to breast cancer." (PMID 29208983, 2017). "LATS1 mRNA levels were not affected by MG in the three breast cancer cell lines." (PMID 27759563, 2016). "However, few studies show that LATS1 is overexpressed in cervical cancers and basal-like breast cancers 26, and the LATS1 methylation statuses do not correlate with survival of lung cancer patients." (PMID 25712415, 2015). "TAZ is also regulated post-translationally, as phosphorylation of TAZ by the kinase LATS1 or LATS2 blocks its nuclear localization and transcriptional activity and it is not clear whether or how inhibition by LATS1/2 is down-regulated in breast cancer." (PMID 25587023, 2014).
breast cancer (continued). "Since loss of WWP1 causes enhanced levels of LATS1 and decreased tumor cell growth, development of strategies that specifically target WWP1 or disrupt LATS1 and WWP1 interaction in breast cancers to activate LATS1 may be a useful approach for successful cancer therapy." (PMID 23573293, 2013). "In the realm of cancer research, lncRNA SNHG9 acts by inhibiting the Hippo pathway through LATS1, while ROR1–human epidermal growth factor receptor 3 (HER3)–lncRNA LLGL2–MAYA–NOP2/Sun RNA methyltransferase 6 is involved in regulating the Hippo–YAP pathway to control bone metastasis in breast cancer." (PMID 40066231, 2025). "Our study identifies YAP/TAZ as the primary signaling effectors downstream of LATS1/2 that drive luminal-basal plasticity in basal-like breast cancer, suggesting that abrogation of YAP/TAZ activity may be beneficial for the treatment of basal-like breast cancers." (PMID 36443313, 2022). "In addition, we derived a basal-like expression signature from human breast cancer samples (TCGA dataset, see the Materials and Methods section) and found it to be up-regulated selectively in the Lats1-CKO PyMT, but not Lats2-CKO tumors (each compared with WT-PyMT littermate control tumors)." (PMID 30456386, 2018). "a-b There was no obvious change in the mRNA expression level of Lats1 when knocking down CRABP2 in ER+ and ER- mammary cancer cells." (PMID 31419991, 2019). "We demonstrated by Western blotting that LATS1, and not LATS2, was significantly decreased upon MG treatment (300 and 500 μM) in both glycolytic MDA-MB-231 and MDA-MB-468 and non-glycolytic MCF7 breast cancer cells." (PMID 27759563, 2016).